USP28 (ubiquitin specific peptidase 28)
Diseases named in the same sentence as USP28 in open-access papers (continued):
Sharing a sentence is not in itself a finding about the gene and the disease.
colitis (1 paper, 2024). Inflammation of the colon. "We then characterized the cytokine profile in the peripheral blood of USP28 deficient and littermate control mice from the colitis experiments." (PMID 39076972, 2024). "In this study we have shown that USP28 plays a protective role in inflammation associated with DSS-induced colitis." (PMID 39076972, 2024). "Because greater weight loss was observed in USP28-/- mice after the first cycle of DSS treatment, we decided to evaluate the effect of USP28 in an acute DSS-induced colitis model." (PMID 39076972, 2024). "Together, USP28 protects mice against early DSS-induced colitis development and long-term intestinal structural integrity." (PMID 39076972, 2024). "In both acute and chronic DSS-induced colitis settings, cytokine levels were comparable between USP28-/- and USP28+/+ mice and the level of IL22 was still increased in USP28-/- mice compared to control mice." (PMID 39076972, 2024). "Together, this suggests a potential regulatory role of USP28 in modulating IL22 and IFNγ expression during acute DSS-induced colitis, with implications for the involvement of the IL2 pathway in this context." (PMID 39076972, 2024). "Our study extends to explore the impact of USP28 on intestinal inflammation using acute and chronic DSS-induced colitis in vivo models." (PMID 39076972, 2024). "In this case, the increased expression of granzyme B and perforin in CD8+ cells would result in a highly cytotoxic profile of these cells in USP28-/- mice, which would be consistent with the exacerbated symptoms seen in acute DSS colitis." (PMID 39076972, 2024). "Since T cells play an essential role in the development of inflammation, to investigate the role of USP28 on T cell effector function, a DSS-induced colitis model was applied to USP28-/- and littermate control mice." (PMID 39076972, 2024). "Our findings demonstrate that USP28 is essential for T cell functionality and protects mice from acute DSS-induced colitis by regulating STAT5 signaling and IL22 production." (PMID 39076972, 2024). "We utilized a USP28 knockout mouse line to study the effect of USP28 on T cell activation and function, and its role in intestinal inflammation using the dextran sulfate sodium (DSS)-induced colitis model and a series of in vitro assays." (PMID 39076972, 2024).
diabetic (1 paper, 2025). "For instance, it has been reported that USP28 deubiquitinates and stabilizes PPARα, thereby preventing mitochondrial morphological and functional defects while improving diabetic myocardial dysfunction." (PMID 41042219, 2025).
diabetic retinopathy (1 paper, 2023). "USP1 in retinal vascular endothelial cells and USP14 in Müller cells are complicating factors for diabetic retinopathy, whereas USP28 in retinal pigment epithelial cells suppresses the progression of retinopathy." (PMID 36834633, 2023).
ductal breast carcinomas (1 paper, 2021). "Furthermore, a positive correlation between USP28 expression and survival was identified in patients with ductal breast carcinomas." (PMID 33664871, 2021).
esophageal cancer (1 paper, 2023). A primary or metastatic malignant neoplasm involving the esophagus. "For example, experiments conducted in human esophageal cancer cells proved that a higher level of USP28 in cells treated with radiotherapy leading to increasing survival of cancer cells, suggesting that USP28 contributes to radiotherapy resistance in esophageal cancer." (PMID 36879346, 2023).
Fanconi anemia (1 paper, 2022). Fanconi anemia (FA) is a hereditary DNA repair disorder characterized by progressive pancytopenia with bone marrow failure, variable congenital malformations and predisposition to develop hematological or solid tumors. "Lung SCCs express elevated levels of USP28, ∆Np63 and several members of FA pathway genes, in agreement with a previous study which showed that ∆Np63 activates the Fanconi Anemia pathway." (PMID 34611298, 2022).
fibrosis (1 paper, 2024). the formation of excess fibrous connective tissue in an organ or tissue in a reparative or reactive process. "Moreover, USP28 knockout in cardiomyocytes mitigated cardiac fibrosis, as assessed by Masson's trichome staining and qPCR assay on mRNA levels of Tgfb and Col1a1." (PMID 39431010, 2024).
glucose metabolic disorders (1 paper, 2019). "Our results reveal that LDHA induces glucose metabolic disorders and stabilizes USP28 expression." (PMID 30688660, 2019).
heart failure (1 paper, 2024). Inability of the heart to pump blood at an adequate rate to meet tissue metabolic requirements. "Overall, cardiomyocyte-specific USP28 knockout ameliorated Ang II-induced heart failure and hypertrophy." (PMID 39431010, 2024). "Here, we applied a recently reported USP28-specific inhibitor OB and showed that selective inhibition of USP28 by OB abrogates TAC-induced established hypertrophic heart failure and oxidative stress, indicating OB as a potential candidate for the treatment of heart failure." (PMID 39431010, 2024).
intestinal tumour (1 paper, 2020).
kidney cancer (1 paper, 2023). Primary or metastatic malignant neoplasm involving the kidney. "High CNV of USP28 was associated with better overall survival in Kidney Cancer, CHOL, and UCEC." (PMID 37450415, 2023).
malignant glioma (1 paper, 2021). A grade III or grade IV glioma arising from the central nervous system. "Moreover, FBXW7‐185aa can interact with the deubiquitinating enzyme USP28 to protect USP28 from interacting with FBXW7α, resulting in shorter half‐life of c‐Myc and inhibiting malignant glioma progression." (PMID 34745938, 2021).
osteosarcoma (1 paper, 2023). A usually aggressive malignant bone-forming mesenchymal neoplasm, predominantly affecting adolescents and young adults. "MVP regulation by USP28 was also confirmed in U2OS osteosarcoma cells, where knockout of USP28 reduced expression of HMGCS1 and resulted in a small but significant decrease in cholesterol levels." (PMID 37202505, 2023).
ovarian carcinoma (1 paper, 2025). A malignant neoplasm originating from the surface ovarian epithelium. "Results from the MTT assay demonstrated that USP28 knockdown heightens the sensitivity of ovarian cancer cells to olaparib." (PMID 40240356, 2025). "In conclusion, these findings suggested that USP28 plays a role in maintaining the stability of SOX9 in ovarian cancer." (PMID 40240356, 2025). "Collectively, the use of a USP28 inhibitor in conjunction with olaparib showed promising potential in overcoming PARPi resistance in ovarian cancer." (PMID 40240356, 2025). "Our further research showed that USP28/SOX9 modulate the HRR activity of ovarian cancer by regulating SMARCA4, UIMC1, and SLX4 expression." (PMID 40240356, 2025). "In the current study, we performed IP/MS and, for the first time, identified deubiquitinase USP28 as a novel SOX9-interacting protein in ovarian cancer." (PMID 40240356, 2025). "Furthermore, inhibition of USP28 was shown to overcome PARPi resistance in ovarian cancer by regulating SOX9 protein stability both in vitro and in vivo." (PMID 40240356, 2025). "Thus, our data indicated that USP28/SOX9 promotes olaparib resistance in ovarian cancer by regulating the DDR activity." (PMID 40240356, 2025). "Thus, our data indicated that USP28 cooperates with SOX9 to promote resistance to olaparib in ovarian cancer." (PMID 40240356, 2025). "To further elucidate the role of USP28 in modulating the sensitivity of ovarian cancer cells to olaparib, we constructed lentivirus-infected ovarian cancer cells with either USP28 knockdown or overexpression, followed by treatment with gradient concentrations of olaparib." (PMID 40240356, 2025). "AZ1 also augmented cell apoptosis triggered by PARPi treatment, suggesting that USP28 inhibition could offer a promising strategy for sensitizing ovarian cancer to PARPi therapy." (PMID 40240356, 2025). "In conclusion, targeted inhibition of USP28 promoted ubiquitination-mediated degradation of SOX9, thereby impairing DNA damage repair capabilities and sensitizing ovarian cancer cells to PARPi." (PMID 40240356, 2025). "In conclusion, these findings suggested that USP28/SOX9 positively regulates the expression of DDR genes (SMARCA4, UIMC1, and SLX4) by binding to their promoters in ovarian cancer cells." (PMID 40240356, 2025). "Furthermore, the USP28 specific inhibitor AZ1 reduced SOX9 protein stability and increased the sensitivity of ovarian cancer cells to olaparib." (PMID 40240356, 2025). "Flow cytometry analysis, colony formation assay, and western blot yielded the similar conclusions that WT USP28 enhances ovarian cancer cells resistance to olaparib, while USP28C171A had no apparent effects." (PMID 40240356, 2025). "In conclusion, our study showed that USP28 directly interacts with SOX9 to decrease its ubiquitination and degradation, which subsequently enhances the DNA damage repair and contributes to PARPi resistance in ovarian cancer cells." (PMID 40240356, 2025). "Further mechanistic studies indicate that targeted inhibition of USP28 using a specific inhibitor leads to ubiquitination-mediated degradation of SOX9, consequently inhibiting DNA damage repair capabilities, and ultimately enhancing the sensitivity of ovarian cancer to PARPi." (PMID 40240356, 2025).
prostate carcinoma (1 paper, 2022). A carcinoma that arises from epithelial cells of the prostate gland. "Identifying the E3 ligase associated with the USP28-PIM axis will help clarify the underlying biology of prostate cancer." (PMID 35326457, 2022). "In the vehicle-treated mice, control tumors grew more rapidly than shUSP28 tumors, indicating that USP28 promotes tumor growth in this prostate cancer model, potentially by inducing PIM1/2 expression." (PMID 35326457, 2022). "These ligases and others may regulate hypoxia-inducible proteins in prostate cancer through USP28." (PMID 35326457, 2022).
sarcoma (1 paper, 2023). A usually aggressive malignant neoplasm of the soft tissue or bone. "Several studies indicate that USP28 is closely related to the progression and prognosis of liver carcinogenesis, GBM, and sarcoma, so we performed Kaplan–Meier curves analysis of ACC, LGG, KICH, and SARC, which indicated that a higher USP28 was associated with poor OS outcomes." (PMID 37450415, 2023).
serous ovarian cancer (1 paper, 2023). "In high-grade serous ovarian cancer cases, Cyclin E1 is connected with chromosomal instability, the overexpression of which is associated with an increased copy number of USP28, although the effect induced by alteration of USP28 is relatively weaker than CCNE1 (encodes Cyclin E1) amplification." (PMID 36879346, 2023).
tumor suppressor (1 paper, 2024).
cancer (72 papers, 2009 to 2026). A tumor composed of atypical neoplastic, often pleomorphic cells that invade other tissues. "USP25 and USP28 are critical deubiquitylases (DUBs) that have been implicated in various diseases, particularly cancer and cardiac dysfunction." (PMID 42017948, 2026). "In conclusion, all tested cancer-associated missense mutations in the C-terminus of USP28 resulted in nuclear exclusion, failure to interact with 53BP1, or protein destabilization; phenotypes which we also observed in cancer-derived cell lines." (PMID 41365927, 2025). "Proline 953 is also often mutated in cancer, supporting the possibility that USP28 is excluded from the nucleus in some cancers." (PMID 41365927, 2025). "To confirm that the tested mutations have similar defects in cancer, we identified four cancer-derived cell lines that have either one homogeneous or two heterogeneous missense mutation in the C-terminus of USP28." (PMID 41365927, 2025). "Loss of functional USP28 allows cells to evade mitotic stress and DNA damage responses in a manner that is specific to cell type and cancer context." (PMID 41365927, 2025). "While frameshift mutations are known to impair USP28 function, most cancer-associated mutations in USP28 are missense mutations, substituting a single amino acid." (PMID 41365927, 2025). "Several cancer-associated mutations in the C-terminus also result in reduced USP28 stability, which likely dampens the mitotic stress response in cancer cells." (PMID 41365927, 2025). "USP25 and USP28, which are highly homologous and associated with diseases like cancer and neurodegenerative disorders, have recently become focal points for the development of therapeutic inhibitors." (PMID 39678489, 2024). "Taken collectively, these findings suggest a broad association between USP28 expression and immunity across various types of cancer." (PMID 37450415, 2023). "To investigate the biological processes associated with USP28 expression in pan-cancer, we conducted differential expression analysis between the top 30% and bottom USP28 expression subgroups in each cancer type." (PMID 37450415, 2023). "The study revealed that USP28 is a risk factor for 19 types of cancer patients and a protective factor for seven types of cancer." (PMID 37450415, 2023). "In this study, we used public databases to explore the expression, mutation, and prognosis profiles of USP28 in various cancers." (PMID 37450415, 2023). "Subsequently, the GSEA was performed on the DEGs in pan-cancer to determine the USP28-associated cancer hallmarks." (PMID 37450415, 2023). "Another significant finding of this study is that the expression of USP28 is significantly associated with immune infiltration in different types of cancers." (PMID 37450415, 2023). "The oncoprotein c-MYC (deregulation of the c-Myc protein is associated with cancer progression, including in lung cancer) is strongly linked to poor patient survival and is stabilized by USP28." (PMID 34502538, 2021). "We hypothesized that missense mutations in USP28 may desensitize cancer cells to mitotic stress, contributing to genome instability, which is a hallmark of cancer." (PMID 41365927, 2025). "USP28 is frequently mutated in cancer and is classified as tumor suppressor 11,35." (PMID 41365927, 2025).
cancer (continued). "Importantly, expression of the R519W variant upregulated γH2AX levels, indicating that cancer-associated mutations can impair USP28 dimerization and contribute to genomic instability in tumor cells." (PMID 38227944, 2024). "USP28 mutations within the dimerization domain occur in a number of human cancers and potentially may affect dimer formation." (PMID 38227944, 2024). "Importantly, we also explored the potential association between the genetic alteration of USP28 and the clinical survival prognosis of cases in some cancers." (PMID 37450415, 2023). "Besides, gene set enrichment analysis was used to analyze the associated cancer hallmarks with USP28 expression, and TIMER2.0 was taken to investigate the immune cell infiltrations related to the USP28 level." (PMID 37450415, 2023). "Moreover, USP28 expression is associated with cancer immunity and clinical survival prognosis." (PMID 37450415, 2023). "The USP28‐targeting small molecule CT1113 exhibits anti‐cancer activity by destabilizing oncogenic NOTCH1 and suppressing SREBP1‐mediated lipogenesis in T‐cell acute lymphoblastic leukemia." (PMID 40855785, 2026). "In summary, these findings indicate that DYRK2 reduces USP28 stability at the protein level, with a potential role in cancer." (PMID 40858801, 2026). "Surprisingly, isoform 2 of USP28 is more dominantly expressed than isoform 1 across 26 cancer cell lines from 10 different tissues." (PMID 41365927, 2025). "By regulating these substrates, USP28 contributes to various processes of cancer, such as tumorigenesis, cell proliferation, DNA damage repair, and chemotherapy resistance." (PMID 40240356, 2025). "In these cancers, USP28-mediated deubiquitination stabilizes important oncogenes including c-MYC, ∆Np63, c-JUN, HIF-1α and NICD indicating an oncogenic function for USP28." (PMID 40456839, 2025). "These seemingly paradoxical roles raise important questions about the context-specific functions of USP28 in cancer." (PMID 41365927, 2025). "Among of them, SLC12A5, MYO1B, FBN1, ITGAV, KLF4 and USP28 were more reported to effect cell proliferation and migration in human cancers." (PMID 39951205, 2025).